GSN (gelsolin)
Diseases named in the same sentence as GSN in open-access papers (continued):
Sharing a sentence is not in itself a finding about the gene and the disease.
neuroblastoma (2 papers, 2015 to 2019). Neuroblastoma (NB) is the most common solid, extracranial childhood tumor. "The same group reported that gelsolin promotes α-synuclein aggregation in the presence of high Ca2+ in neuroblastoma cells." (PMID 31527695, 2019). "In spite of differences, both these aggregates displayed reduced toxicity against SH-SY5Y human neuroblastoma cells as compared to control gelsolin amyloids." (PMID 25996685, 2015).
ovarian serous adenocarcinoma (2 papers, 2021 to 2023). An adenocarcinoma that arises from the ovary and is characterized by the presence of malignant epithelial cells that, in well differentiated tumors, resemble the epithelium of the fallopian tube or, in poorly differentiated tumors, show anaplastic features and marked nuclear atypia. "High GSN expression has been shown to significantly correlate with longer OS and PFS in all-stage patients and subgroups with serous ovarian cancer." (PMID 37046833, 2023).
pulmonary diseases (2 papers, 2013 to 2024). "Increasingly evidence has shown that gelsolin has close relationship with many diseases and pathological processes, such as cancer, apoptosis, infection and inflammation, pulmonary diseases, and aging." (PMID 23533533, 2013). "However, this study is the first to demonstrate alterations of GSN at the transcriptional and protein levels in CS-induced lung disease and COPD in mice and humans." (PMID 39352744, 2024). "Using the LOVE/SLIDE interpretable machine learning approach, we identified previously unknown epithelial cell–specific transcriptional rewiring of the actin-modifying gene GSN in CS-related lung disease and demonstrate its function in epithelial cells in COPD." (PMID 39352744, 2024).
renal fibrosis (2 papers, 2016 to 2022). A final common manifestation of a wide variety of chronic kidney diseases characterized by glomerulosclerosis and tubulointerstitial fibrosis. "For example, upregulation of DEPs VIM, IQGAP1, and moesin is closely related to EMT and renal fibrosis, and GSN, another DEP, is related to renal tubule epithelial cell apoptosis." (PMID 27036204, 2016).
schizophrenia (2 papers, 2016 to 2020). A major psychotic disorder characterized by abnormalities in the perception or expression of reality. "The presumption that Sox10 could influence GSN expression is additionally supported by the fact that in patients with schizophrenia the SOX10 methylation level was inversely correlated with the expression level of several “oligodendrocyte” genes including GSN." (PMID 25352156, 2016).
squamous carcinomas (2 papers, 2003 to 2006). "For gelsolin, high expression was associated with sex (female patients: 66.7% vs. 51.2%), and histology (squamous carcinomas: 38.1% vs. 26.7%)." (PMID 16882345, 2006).
steatosis (2 papers, 2017 to 2025). Increased lipid within the cytoplasm of cells. "To investigate the potential role of GSN in MASH, we initially examined the transcription levels of GSN in human liver samples categorized as normal control, healthy obese, steatosis, and MASH." (PMID 40390546, 2025). "This suggests that although GSN alleviates fibrosis and inflammation partly by suppressing YAP activity, its effects on steatosis may be mediated through independent signaling pathways." (PMID 40390546, 2025).
thrombosis (2 papers, 2019 to 2025). "The thrombo-protective capability of exogenous gelsolin was demonstrated in models of ferric chloride-induced thrombosis of the carotid artery and thrombin-induced acute pulmonary thromboembolism in mice." (PMID 40106086, 2025). "The present study provides first evidence on the role of plasma gelsolin in protecting pulmonary thromboembolism and thrombosis in a mouse model." (PMID 31002695, 2019). "In thrombosis model, arterial occlusion time was significantly enhanced upon subcutaneous (SC) treatment with 8 mg of gelsolin per mice viz." (PMID 31002695, 2019).
tick-borne encephalitis (2 papers, 2014 to 2018). Tick-borne encephalitis is caused by an arbovirus of the Flaviviridae family (tick-borne encephalitis virus, TBEV), transmitted principally by the bite of the Ixodes ricinus tick. "An inflammatory reaction accompanied by central nervous system (CNS) infections such as tick-borne encephalitis (TBE) or Lyme neuroborreliosis (LNB), also results in blood and cerebrospinal fluid (CSF) alterations in plasma gelsolin." (PMID 25421616, 2014).
ulcerative colitis (2 papers, 2022 to 2023). An inflammatory bowel disease involving the mucosal surface of the large intestine and rectum. "In contrast to our finding where gelsolin was higher in diseased dogs, gelsolin has an inverse relationship with clinical and endoscopic activity in patients with ulcerative colitis, its level was significantly lower in ulcerative colitis patients compared to healthy controls." (PMID 37186013, 2023). "The serum gelsolin level in patients with ulcerative colitis was significantly lower than that in healthy subjects, and it decreased in proportion to increasing Mayo score and Mayo endoscopic subscore." (PMID 35453622, 2022). "Our findings indicate that the serum gelsolin level correlates with clinical and endoscopic activities in ulcerative colitis, has a higher sensitivity and specificity than C-reactive protein, and can detect mucosal healing, suggesting that gelsolin can be used as a biomarker for ulcerative colitis." (PMID 35453622, 2022).
acute coronary syndrome (1 paper, 2013). Signs and symptoms related to acute ischemia of the myocardium secondary to coronary artery disease. "Studies have also shown that platelet gelsolin is highly expressed in patients with acute coronary syndrome (ACS) and the blood-stasis syndrome (BSS) of traditional Chinese medicine (TCM)." (PMID 23533533, 2013). "In addition, data from our previous clinical studies demonstrated that platelet gelsolin was highly expressed in patients with acute coronary syndrome (ACS) and the blood stasis syndrome (BSS) of traditional Chinese medicine." (PMID 23533533, 2013).
acute pancreatitis (1 paper, 2023). An acute inflammatory process that leads to necrosis of the pancreatic parenchyma. "This study investigated how GSN-regulated actin filaments control autophagy in pancreatic ductal epithelial cells (PDECs) in acute pancreatitis (AP)." (PMID 36722658, 2023).
AIDS (1 paper, 2018). A syndrome resulting from the acquired deficiency of cellular immunity caused by the human immunodeficiency virus (HIV). "In summary, gelsolin is strongly induced upon HIV infection and gelsolin plasma levels show clinical predictive value for progression of AIDS." (PMID 29401736, 2018).
allergic asthma (1 paper, 2011). A asthma with a basis in a pathological type I hypersensitivity reaction. "It is localized on chromosome 9q33.2, in LD with two other genes that regulate inflammation and significantly associated with allergic asthma, GSN and RAB14." (PMID 21359210, 2011).
anxiety disorder (1 paper, 2018). A category of psychiatric disorders which are characterized by anxious feelings or fear often accompanied by physical symptoms associated with anxiety. "Our results suggests that the ATF3-Gelsolin pathway controls the synaptic transmission of fear memory possibly through actin polymerization and maintains fear responses at an optimal level to prevent anxiety disorders." (PMID 29515366, 2018).
autism (1 paper, 2016). Persistent deficits in social interaction and communication and interaction as well as a markedly restricted repertoire of activity and interest as well as repetitive patterns of behavior. "Previous studies have indicated that several differential alternative splicing genes (DAS), such as FXR1, C19orf2, GSN, and SRPK1, are associated with autism." (PMID 28000768, 2016).
Barrett’s oesophagus (1 paper, 2025). "Geloslin, a known tumour suppressor gene, is a multifunctional regulator of cell structure and GSN downregulation in a glycoprotein panel is a diagnostic biomarker for Barrett’s oesophagus requiring clinical intervention." (PMID 40640495, 2025).
bladder tumors (1 paper, 2013). "The proteomic approach identified differential expression of proteins previously linked with aggressive clinical outcome in bladder tumors: gelsolin, moesin, Ezrin, caveolin, Filamin A." (PMID 23308193, 2013).
brain cancer (1 paper, 2023). A primary or metastatic malignant neoplasm affecting the brain. "In summary, this study provides the novel fundamental idea of a specific regulatory mechanism of aggressive brain cancer cell migration through the relationship between mTORC2 and GSN." (PMID 37120454, 2023). "To further prove whether GSN-RICTOR and MYH9-RICTOR interactions are associated with cell migrational control, we also determined cell migration ability in two additional cell lines, DBTRG-05MG and SW1088 representing high-grade and low-grade brain cancer cells." (PMID 37120454, 2023). "However, the molecular and biological functions of GSN in brain cancer have not been clearly defined." (PMID 37120454, 2023).
brain injury (1 paper, 2011). Acute and chronic (see also brain INJURIES, CHRONIC) injuries to the brain, including the cerebral hemispheres, CEREBELLUM, and brain STEM. "At 24 h pb, dispersed leukocytes were still observed in the cortex of Gsn-L mice, suggesting that treatment with gelsolin at low dose fails to ameliorate the burn-induced brain injury." (PMID 21936896, 2011).
co-infection (1 paper, 2019). "TYLCV&ToCV co-infection induced the expression of the gelsolin gene, an important actin regulator that is associated with the inhibition of apoptosis." (PMID 31001125, 2019).
colorectal polyp (1 paper, 2023). "The present study's findings suggest that the expression pattern of CDC42, TAGLN, and GSN genes was significantly increased during the transformation of normal tissue to polyp lesions, indicating their potential as prognostic biomarkers for colorectal polyp development." (PMID 37365287, 2023).
colorectal tumor (1 paper, 2012). "We investigated the influence of gelsolin on colorectal tumor cell dissemination and the mechanisms underlying its pro-invasive activity." (PMID 22927998, 2012). "In addition gelsolin expression was reduced using siRNA knockdown in several colorectal tumor cell lines (HCT116 and its metastatic variant E1, gelsolin-overexpressing HCT116, DLD-1 and Caco-2), and compared to cells transfected with control siRNA." (PMID 22927998, 2012). "uPA and its receptor uPAR were further determined to be crucial for gelsolin-dependent invasion in colorectal tumor cells." (PMID 22927998, 2012). "The effects of gelsolin overexpression and knockdown in colorectal tumor cells were determined as described in the sections below." (PMID 22927998, 2012). "We have demonstrated here that gelsolin is crucial for the invasive behavior of colorectal tumor cells." (PMID 22927998, 2012). "In summary, our data reveals novel functions of gelsolin in colorectal tumor cell invasion through its modulation of the uPA/uPAR cascade, with potentially important roles in colorectal tumor dissemination to metastatic sites." (PMID 22927998, 2012). "Our work thus elucidates a novel role for gelsolin in colorectal tumor dissemination, by modulation of the uPA cascade which is crucial for invasion." (PMID 22927998, 2012). "The oncogenic potential of gelsolin in colorectal tumor cells was investigated by modulating gelsolin levels using gelsolin overexpression and siRNA knockdown." (PMID 22927998, 2012). "Conversely, siRNA knockdown of gelsolin in the colorectal tumor cell lines HCT116, DLD-1 and Caco-2 significantly reduced the level of secreted uPA and its proteolytic activity." (PMID 22927998, 2012). "We analyzed the expression of gelsolin by IHC in 24 primary colorectal tumors and 26 colorectal liver metastases as well as 15 normal tissues from the surgical margins of clearance." (PMID 22927998, 2012). "The effects of gelsolin in human colorectal tumor cells were examined by inducing gelsolin overexpression as well as silencing with siRNA." (PMID 22927998, 2012). "It is unknown if gelsolin also regulates non-nuclear receptor-dependent transcription, though its presence in the nuclei of colorectal tumor tissues suggests wider roles for nuclear-associated gelsolin." (PMID 22927998, 2012). "Interestingly we also observed high gelsolin expression in infiltrating clusters of less-differentiated cells, some of which appeared to be breaking away from well-formed glandular structures, supporting the hypothesis that gelsolin is involved in colorectal tumor cell invasion and dissemination." (PMID 22927998, 2012).
Crohn disease (1 paper, 2023). A gastrointestinal disorder characterized by chronic inflammation involving all layers of the intestinal wall, noncaseating granulomas affecting the intestinal wall and regional lymph nodes, and transmural fibrosis. "Higher gelsolin concentrations is found in intestinal smooth muscle cells in people with Crohn's disease, suggesting an ongoing inflammatory process." (PMID 37186013, 2023).
cystic fibrosis (1 paper, 2018). Autosomal recessive disorder caused by pathogenic variants in the CFTR gene (cystic fibrosis transmembrane conductance regulator), which encodes a chloride and bicarbonate channel expressed in epithelial cells, and follow the diagnosis criteria. "Despite the promising results showing the significant prognostic and therapeutic potential of gelsolin, the most advanced clinical research has focused on the application of plasma gelsolin as a mucolytic agent aimed to decrease the abnormal viscoelasticity of cystic fibrosis sputum." (PMID 30149613, 2018).
cystic tumors (1 paper, 2023). "We detected in the cystic fluid of all tumors some proteins that are already known to play a role in one or more of the cystic tumors studied: gelsolin (GSN), haptoglobin (HP), alpha-2-HS-glycoprotein (AHSG) and alpha-1-antichymotripsin (AACT)." (PMID 37627098, 2023).
deafness (1 paper, 2017). An inherited or acquired condition characterized by the complete loss of the ability to hear from one or both ears. "Support for a role of RPGR and gelsolin in ciliary function and rhodopsin trafficking comes from work examining Usher Syndrome, a syndromic form of RP and deafness." (PMID 28814713, 2017).
depression (1 paper, 2020). "Third, we found that the plasma proteins GSN and C4B were biomarkers of depression, similar to findings in previous studies using the same LC-MS platform." (PMID 33126421, 2020).
diabetic nephropathy (1 paper, 2020). "Therefore, the reduction of gelsolin found in our study may be responsible for the glomerular alteration in diabetic nephropathy." (PMID 32665774, 2020).
dry eye (1 paper, 2019). "GSN and PFN1 have also been shown to be upregulated particularly in aqueous-deficient dry eye with and without lipid deficiency, but not in lipid-deficient dry eye alone." (PMID 30976209, 2019).
endotoxemia (1 paper, 2019). "Neutralization of endotoxemia-mediated cellular effects by gelsolin-derived peptides and PBP10-containing nanosystems might be considered as potent therapeutic agents in the improved therapy of bacterial infections and microbial-induced inflammation." (PMID 30711007, 2019).
erythrocytosis (1 paper, 2021). "ET in children is very rare but has been reported and must be distinguished from hereditary erythrocytosis, which involves germline mutations in JAK2 or GSN (gelsolin gene)." (PMID 34833034, 2021).
essential thrombocythemia (1 paper, 2020). A chronic myeloproliferative neoplasm that involves primarily the megakaryocytic lineage. "Even though platelets secrete gelsolin, the cases with essential thrombocythemia, which has extremely high levels of platelets, showed low levels of GSN mRNA, suggesting that platelets in myeloproliferative neoplasms (MPN) might be abnormal regarding gelsolin." (PMID 32992584, 2020).
Hyperglycemia (1 paper, 2024). An increased concentration of glucose in the blood. "We hypothesized that these genes might be relevant to the systemic effects of hyperglycemia, and in particular, four genes were upregulated across many cell types and organs in STZ mice: the proteoglycan decorin (Dcn), gelsolin (Gsn), matrix Gla protein (Mgp), and metallothionein 1 (Mt1)." (PMID 38305779, 2024).
idiopathic interstitial pneumonia (1 paper, 2018). A class of diffuse lung diseases that typically affect the pulmonary interstitium, although some also have a component affecting the airways (for instance, Cryptogenic organizing pneumonitis). "Gelsolin expression is altered in cancer, inflammation, idiopathic interstitial pneumonia and Alzheimer’s disease." (PMID 30254298, 2018).
idiopathic pneumonia syndrome (1 paper, 2018). "Plasma gelsolin levels also drop shortly after hematopoietic stem cell transplantation, and bone marrow transplant patients are more likely to develop respiratory complications, including idiopathic pneumonia syndrome (IPS)." (PMID 30149613, 2018).
Immunodeficiency (1 paper, 2021). Failure of the immune system to protect the body adequately from infection, due to the absence or insufficiency of some component process or substance. "ABPs such as gelsolin, Tβ4, filamin, villin-1, gelsolin, profilin-1, SYNPO, and cortactin are abnormally expressed in certain inflammatory environments, where they inhibit or induce immunodeficiency inflammation." (PMID 34194957, 2021).
inflammatory skin disease (1 paper, 2023). Inflammatory skin disorders covers a broad category that includes many conditions ranging in severity, from mild itching to grave medical health complications These disorders are common in people of all ages and races. "The role of gelsolin in various inflammatory skin diseases including psoriasis has yet to be clearly established." (PMID 36902587, 2023).
influenza (1 paper, 2019). An acute viral infection of the respiratory tract, occurring in isolated cases, in epidemics, or in pandemics; it is caused by serologically different strains of viruses (influenzaviruses) designated A, B, and C, has a 3-day incubation period, and usually lasts for 3 to 10 days. "NCBI Gene Expression Omnibus: Transcriptome profiling of lung tissue from influenza-infected mice treated with plasma gelsolin." (PMID 31824672, 2019).
intestinal tumors (1 paper, 2016). "It was found that gelsolin expression was higher in a subset of lymph node metastases compared to their primary intestinal tumors." (PMID 27058427, 2016).
laryngeal carcinoma (1 paper, 2022). Carcinoma that arises from the laryngeal epithelium. "Our aim in this research was to clarify the relationship between gelsolin and laryngeal cancer and to investigate the usability of gelsolin as a novel biomarker to predict prognosis in LSCC." (PMID 34144901, 2022). "Gelsolin expression status was found to have a statistically significant relationship in the prognosis of laryngeal cancer." (PMID 34144901, 2022). "•Gelsolin expression was higher in patients with advanced-stage laryngeal carcinoma." (PMID 34144901, 2022). "This study also reveals that new therapeutic agents targeting gelsolin protein may be useful to treat laryngeal cancer more effectively." (PMID 34144901, 2022).
liver cirrhosis (1 paper, 2018). "An interesting study proposed plasma gelsolin as a biomarker for hepatitis B-associated liver cirrhosis." (PMID 30149613, 2018). "To date, proteomic analyses comparing the plasma proteome of inactive HBV-infected patients and patients suffering from HBV-associated liver cirrhosis confirmed repression of gelsolin in cirrhotic plasma samples." (PMID 30149613, 2018). "Further investigations are needed to confirm the utility of gelsolin as a prognostic marker or a therapeutic agent in liver cirrhosis." (PMID 30149613, 2018).